COMMD6 (COMM domain containing 6)
Description:
Scaffold protein in the commander complex that is essential for endosomal recycling of transmembrane cargos; the commander complex is composed of the CCC subcomplex and the retriever subcomplex. May modulate activity of cullin-RING E3 ubiquitin ligase (CRL) complexes. Down-regulates activation of NF-kappa-B. Inhibits TNF-induced NFKB1 activation.
Synonyms: Acrg
Tractability: PROTAC: ubiquitination databases record sites on it.
Gene: Protein-coding gene on chromosome 13 (75,525,214 to 75,549,439, reverse strand). Ensembl gene ENSG00000188243.
Subcellular location: Nucleus; Cytoplasm
Pathways (Reactome):
Metabolism of proteins: Neddylation
Gene Ontology:
Molecular function: NF-kappaB binding; protein binding
Biological process: negative regulation of transcription by RNA polymerase II; endocytic recycling; signal transduction
Cellular component: nucleus; protein-containing complex; endoplasmic reticulum membrane; endosome membrane; cytoplasm
Genetic constraint (gnomAD): Loss-of-function variants: 3 observed, 4.82 expected, observed/expected ratio (o/e) 0.62, 90% interval 0.28 to 1.54. That is too few expected variants to judge how well the gene tolerates losing a copy. Missense variants: 43 observed, 23.96 expected, observed/expected ratio (o/e) 1.79, 90% interval 1.37 to 1.97. Synonymous variants: 15 observed, 11.57 expected, observed/expected ratio (o/e) 1.3, 90% interval 0.86 to 1.85.
Homologues: Orthologues: macaque COMMD6 (99% identical), dog COMMD6 (92% identical), rabbit COMMD6 (86% identical), rat Commd6 (86% identical), mouse Commd6 (85% identical), guinea pig COMMD6 (67% identical), zebrafish commd6 (62% identical), tropical clawed frog commd6 (55% identical). Paralogues in human: COMMD7 (28% identical), COMMD8 (25% identical).
Diseases named in the same sentence as COMMD6 in open-access papers:
COMMD6 is named in the same sentence as 32 diseases in open-access papers, as found by Europe PMC text mining. Sharing a sentence is not in itself a finding about the gene and the disease. The quoted sentences say what the papers report.
adrenocortical carcinoma (3 papers, 2019 to 2023). "High COMMD6 expression is associated with shorter OS and DFS in patients with head and neck squamous cell carcinoma, cholangiocarcinoma and adrenocortical carcinoma, but is associated with longer OS and DFS in patients with low-grade glioma and uveal melanoma." (PMID 34493238, 2021). "Eleven types of cancer, including adrenocortical carcinoma, pheochromocytoma and paraganglioma and ovarian cancer, showed lower levels of COMMD6 expression than their healthy counterparts." (PMID 34493238, 2021). "Eleven types of tumours expressed lower COMMD6 compared to normal tissues, especially in adrenocortical carcinoma, pheochromocytoma and paraganglioma and ovarian cancer." (PMID 31523056, 2019). "COMMD6 was discovered to be highly expressed in 20 types of tumors, such as colon cancer and brain lower grade glioma (LGG), and to be poorly expressed in 11 other types of tumors, including adrenocortical carcinoma (ACC) and pheochromocytoma." (PMID 36776284, 2023).
cholangiocarcinoma (3 papers, 2019 to 2023). A carcinoma that arises from the intrahepatic biliary tree (intrahepatic cholangiocarcinoma) or from the junction, or adjacent to the junction, of the right and left hepatic ducts (hilar cholangiocarcinoma). "Furthermore, we shed light on the underlying tumour promoting role and mechanism of COMMD6 by constructing a TEX41-miR-340-COMMD6 ceRNA network in head and neck squamous cell carcinoma and miR-218-CDX1-COMMD6 transcriptional network in cholangiocarcinoma." (PMID 31523056, 2019).
head and neck squamous cell carcinoma (3 papers, 2019 to 2021). A squamous cell carcinoma that arises from any of the following anatomic sites: lip and oral cavity, nasal cavity, paranasal sinuses, pharynx, larynx, and salivary glands. "Specifically, in head and neck squamous cell carcinoma, the expression level of TEX41 is higher than in normal tissues where, by means of inhibiting the expression of the known tumor suppressor miR-340, it induces the expression of COMMD6." (PMID 34233751, 2021).
uveal melanoma (3 papers, 2019 to 2023). A melanoma derived from melanocytes of the uveal tract. "In contrast, high expression of COMMD6 was associated with longer OS and DFS in patients with brain lower grade glioma (LGG, P = 0.0016 and HR = 0.56 for OS; P = 0.0096 and HR = 0.66 for DFS) and uveal melanoma (UVM, P = 0.0085 and HR = 0.30 for OS; P = 0.028 and HR = 0.35 for DFS)." (PMID 31523056, 2019).
colorectal cancer (2 papers, 2019 to 2021). A primary or metastatic malignant neoplasm that affects the colon or rectum. "The median expression of COMMD6 mRNA was higher in 20 types of human tumours compared to corresponding normal tissues, such as colorectal cancer, brain lower grade glioma and acute myeloid leukaemia." (PMID 31523056, 2019). "The mRNA expression of COMMD6 is higher in 20 types of human cancer, such as HCC, colorectal cancer (CRC), and low-grade glioma than in their corresponding healthy tissues." (PMID 34493238, 2021). "Both mRNA expression and CNV of COMMD6 were highest in acute myelocytic leukaemia (AML), meningioma, colorectal cancer and diffuse large B-cell lymphoma (DLBCL) cell lines." (PMID 31523056, 2019).
gastric cancer (2 papers, 2022 to 2024). A primary or metastatic malignant neoplasm involving the stomach. "As depicted in, except for COMMD1 and COMMD6, the remaining COMMD genes included in the study exhibited significant differential expression in gastric cancer." (PMID 38817875, 2024).
thyroid carcinoma (2 papers, 2019 to 2023). "In addition, high expression of COMMD6 was associated with longer OS in patients with testicular germ cell tumours (TGCT, P = 0.05, HR = 1.7E-09), longer DFS in patients with thyroid carcinoma (THCA, P = 0.017, HR = 0.48) and uterine corpus endometrial carcinoma (UCEC, P = 0.029, HR = 0.47)." (PMID 31523056, 2019).
Ewing sarcoma (1 paper, 2019). A small round cell tumor that lacks morphologic, immunohistochemical, and electron microscopic evidence of neuroectodermal differentiation. "In addition, the methylation status of COMMD6 was highest in lymphocyte malignancies, and lowest in soft tissue cancer, osteosarcoma, leukaemia, giant cell tumour, Ewing’s sarcoma and oesophagus cancer cell lines." (PMID 31523056, 2019).
melanoma (1 paper, 2019). A malignant, usually aggressive tumor composed of atypical, neoplastic melanocytes. "COSMIC database analysis showed that COMMD6 was highly mutated in skin cancer, soft tissue cancer and melanoma cells." (PMID 31523056, 2019).
rectal cancer (1 paper, 2019). A primary or metastatic malignant neoplasm that affects the rectum. "In contrast, rare mutation of COMMD6 was observed in cervical, colon and rectal cancer cells." (PMID 31523056, 2019).
cancer (4 papers, 2019 to 2023). A tumor composed of atypical neoplastic, often pleomorphic cells that invade other tissues. "More importantly, the expression of COMMD6 was associated with the survival of cancer patients." (PMID 31523056, 2019). "In a recent study, researchers used the GEPIA database to evaluate COMMD6 mRNA expression in 31 human cancers with matching normal tissue species." (PMID 36776284, 2023). "The overexpression of COMMD6 can either improve or worsen the cancer prognosis depending on the cancer type." (PMID 34943955, 2021). "COMMD6 is the most well-studied member of the COMMD proteins in human cancer." (PMID 34493238, 2021). "More importantly, the expression of COMMD6 could predict the survival of cancer patients, indicating the significant role of COMMD6 in tumour development and progression." (PMID 31523056, 2019). "COMMD6 expression was widely observed in BALB/c mice and human tissues, which predicted prognosis of cancer patients." (PMID 31523056, 2019).
tumor (2 papers, 2019 to 2021). "Furthermore, we shed light on the underlying tumour promoting role and the mechanism of COMMD6 by constructing a TEX41-miR-340-COMMD6 ceRNA network in HNSC and miR-218-CDX1-COMMD6 transcriptional network in CHOL." (PMID 31523056, 2019). "In contrast, COMMD6 was highly expressed in the cytoplasm of human breast, liver and kidney normal tissues while negatively expressed in corresponding tumour tissues." (PMID 31523056, 2019). "To further explore the potential upstream mechanism of COMMD6 involved in tumour progression, we presented a transcriptional regulatory network and 62 transcription factors (TFs) that participate in the regulation of COMMD6 expression." (PMID 31523056, 2019). "Here, we provided the tissue-specific expression, biology function and the possible mechanism of COMMD6 in a variety of tissues, aiming to elucidate its functions and clinical values in human tumours." (PMID 31523056, 2019). "COMMD6 protein was negatively expressed in both tumour tissues and corresponding normal tissues of stomach, bladder, lung and oesophagus." (PMID 31523056, 2019). "We further detected the expression of COMMD6 protein in eight types of human paired tumour and normal tissues by IHC assay." (PMID 31523056, 2019). "A significantly higher level of COMMD6 was found in tumours compared to normal tissues, indicating a tumour promoting role of COMMD6 in HNSC." (PMID 31523056, 2019). "The expression level of COMMD6 mRNA was further exhibited in 31 types of human paired tumour and normal tissues using GEPIA database." (PMID 31523056, 2019). "Here, we provided the expression profile data and bioprediction information of COMMD6 in a variety of tissues, which help to elucidate its functions and clinical values in various human tumours." (PMID 31523056, 2019). "In colon, COMMD6 was highly expressed in the cytoplasm of tumour tissues while negatively expressed in normal mucosa." (PMID 31523056, 2019). "As a prototype for the COMMD family, the expression pattern and biological function of COMMD6 in human tumours remain unknown." (PMID 31523056, 2019). "COMMD6 was significantly higher in tumour tissues compared to normal tissues." (PMID 31523056, 2019). "However, there were some differences in the expression of COMMD6 in tumour and normal tissues between GEPIA database and our IHC results." (PMID 31523056, 2019). "This study may help to elucidate the functions and mechanisms of COMMD6 in various human tumours, providing a potential biomarker for tumour prevention and therapy." (PMID 31523056, 2019). "Kaplan–Meier analysis was applied to evaluate the prognosis of COMMD6 in tumours." (PMID 31523056, 2019). "We further analysed the expression of COMMD6 in human tumours by using GEPIA database." (PMID 31523056, 2019). "Ten tumours expressed higher level, while 21 tumours showed lower level of COMMD6 mRNA compared to corresponding normal counterparts, implying that different mechanisms are involved in the regulation of COMMD6 expression in the development of human tissues." (PMID 31523056, 2019). "This study may help to elucidate the functions and mechanisms of COMMD6 in human tumours, providing a potential biomarker for tumour prevention and therapy." (PMID 31523056, 2019). "Furthermore, the expression of COMMD6 in eight kinds of tumours and matched normal specimens were examined using IHC to verify the GEPIA result." (PMID 31523056, 2019). "In addition, we found that COMMD6 may modulate the ubiquitination and degradation of NF-κB subunits and regulate ribonucleoprotein and spliceosome complex biogenesis in tumours." (PMID 31523056, 2019). "In addition, COMMD6 may modulate the ubiquitination and degradation of NF-κB subunits and regulate ribonucleoprotein and spliceosome complex biogenesis in tumours." (PMID 31523056, 2019). "However, the tissue-specific expression, biology function and the possible mechanism of COMMD6 in tumour remain unknown." (PMID 31523056, 2019).
tumor (continued). "However, rare evidence has been reported about the role of COMMD6 in tumours." (PMID 31523056, 2019). "In conclusion, our study firstly illuminated the expression profile of COMMD6 in BALB/c mice and primary human normal and tumour tissues." (PMID 31523056, 2019). "As the most commonly used laboratory animals to investigate human tumours, BALB/c mice were further investigated for the expression and distribution of COMMD6." (PMID 31523056, 2019).
COMMD6 also shares sentences with these, for which no sentence is quoted: pheochromocytoma (3 papers); ovarian carcinoma (2); paraganglioma (2); uterine corpus endometrial carcinoma (2); acute myeloid leukaemia (1); breast carcinoma (1); colon cancer (1); diffuse large B-cell lymphoma (1); giant cell tumour (1); glioma (1); head and neck cancer (1); leukaemia (1); meningioma (1); oesophagus cancer (1); osteosarcoma (1); Sepsis (1); skin cancer (1); testicular germ cell tumor (1); testicular germ cell tumours (1); urticaria (1).